AHR (aryl hydrocarbon receptor)
Diseases named in the same sentence as AHR in open-access papers (continued):
Sharing a sentence is not in itself a finding about the gene and the disease.
osteoporosis (16 papers, 2015 to 2025). A condition of reduced bone mass, with decreased cortical thickness and a decrease in the number and size of the trabeculae of cancellous bone (but normal chemical composition), resulting in increased fracture incidence. "Studies have shown that in models of osteoporosis caused by hormone deficiency, isopsoralen acts as an AhR antagonist, increases the expression of ERα, enhances bone strength and trabecular bone structure, and promotes osteoblast differentiation through the AhR/ERα pathway." (PMID 39902075, 2024). "Elucidation of AhR function in human osteoclasts will introduce a potential therapeutic target for various human diseases in which osteoclasts are implicated in pathogenesis, including bone destructive diseases such as osteoporosis and cancer." (PMID 33066667, 2020). "Further research on osteoclastic AhR antagonists should be able to help provide more information on the development of tools that could be useful in the prevention and treatment of osteoporosis caused by environmental pollutants." (PMID 25615839, 2015). "Taken together, the AhR pathway mediates excessive osteoclastic differentiation and bone resorption caused by smoking exposure, which could be a potential target for the prevention of smoking-induced osteoporosis." (PMID 35627191, 2022). "Recent studies have shown that endogenous activation of the AhR has multiple roles in the regulation of bone remodeling and its associated signaling pathways, which may be an essential mechanism for smoking-induced osteoporosis." (PMID 35627191, 2022). "Kynurenine and indoxyl sulfate could exacerbate osteoporosis by decreasing bone strength and affecting osteoclastogenesis through AhR-associated mechanisms, respectively, the inhibition of which might provide new opportunities for the treatment of osteoporosis in CKD." (PMID 35656117, 2022). "Another study demonstrated the anti-osteoporosis activity of Rb1 in dexamethasone (DEX)-induced osteoporosis rat model by regulating aryl hydrocarbon receptor (AHR)/proline/arginine-rich end leucine-rich repeat protein (PRELP)/NF-κB signaling pathway." (PMID 40507179, 2025). "From the perspective of osteoporosis phenotypes, supplementation with IAA and IPA effectively ameliorated bone loss of OVX mice in an intestinal AhR‐dependent manner." (PMID 39041942, 2024). "Isopsoralen (IPRN), a key bioactive compound found in Psoralea corylifolia Linn, functions as an AHR antagonist and enhances osteoblast differentiation through the AHR/ERα axis in an osteoporosis model." (PMID 39575260, 2024). "On the other hand, AhR signaling is involved in many processes promoting cellular senescence and pathological processes, e.g., osteoporosis, vascular dysfunction, and the age-related remodeling of the immune system." (PMID 35987825, 2022). "On the other hand, with aging, AhR signaling increases cellular senescence and osteoporosis, inhibits autophagy, and disturbs vascular homeostasis." (PMID 35987825, 2022). "There is substantial evidence that with aging, AhR factor is involved in several processes promoting cellular senescence and age-related pathological conditions, such as osteoporosis, vascular dysfunction, and the remodeling of the immune system." (PMID 35987825, 2022). "Treating the animals with AHR agonists further reduced bone formation, potentially representing a contributory mechanism in osteoporosis." (PMID 32194572, 2020). "There is abundant evidence that the activation of AhR signaling arrests the proliferation of human osteoblasts, whereas it stimulates the formation of osteoclasts thus increasing bone resorption and enhancing osteoporosis with aging." (PMID 35987825, 2022). "The inhibition of the AhR pathway could be a promising strategy for CS-induced osteoporosis." (PMID 35627191, 2022).
osteoporosis (continued). "In the current study, we investigated the role of peripheral TRP catabolism, aryl hydrocarbon receptor (AhR) as a physiological receptor for KYN and AhR-dependent cytochrome P450 1A1 (CYP1A1) in the development of osteoporosis in CKD." (PMID 29163188, 2017). "Multiple linear regression analysis performed only on the osteoporosis cohort without a history of ONJ (n = 79) indicated that the length of time on N-BP therapy, but not age, was significantly linked to both higher RANK (β = 0.233, p = 0.045) and AHR (β = 0.247, p = 0.032) gene expression." (PMID 26141514, 2015).
pancreatic ductal adenocarcinoma (16 papers, 2022 to 2026). An infiltrating adenocarcinoma that arises from the epithelial cells of the pancreas. "Conversely, tryptophan metabolites from indole-producing bacteria, including Lactobacillus spp., have been found to suppress ICB responses in mice with pancreatic ductal adenocarcinoma (PDAC) through the induction of AHR signaling in macrophages." (PMID 40264971, 2025). "Tumor-associated macrophage (TAM) exhibits high AhR activity, and inhibiting AhR in TAM reduces pancreatic ductal adenocarcinoma (PDAC) growth." (PMID 38462620, 2024). "The depletion of AHR in myeloid cells or the inhibition of AHR by antagonistic treatment reduces the progression of pancreatic ductal adenocarcinoma (PDAC) by diminishing the immunosuppressive function of TAMs and enhancing immune surveillance by CD8+ T cells." (PMID 38612627, 2024). "To evaluate if the observed effects of BAY2416964 were limited to PyMT cells, we examined the ability of BAY2416964 to inhibit AHR signaling in the murine pancreatic ductal adenocarcinoma cell line CR705." (PMID 39450255, 2024). "Lactobacillus metabolism of dietary tryptophan to indoles enhances the activity of the aryl hydrocarbon receptor (AhR) in TAMs in pancreatic ductal adenocarcinoma (PDAC)." (PMID 39516356, 2024). "The aryl hydrocarbon receptor (AHR) is a transcription factor that is commonly upregulated in pancreatic ductal adenocarcinoma (PDAC)." (PMID 37685961, 2023). "This study investigated the role of aryl hydrocarbon receptor (AHR) expression in pancreatic ductal adenocarcinoma patients’ peripheral blood immune cells." (PMID 37760608, 2023). "Activation of aryl hydrocarbon receptor (AhR) can promote TAMs from pancreatic ductal adenocarcinoma (PDAC) to immunosuppressive phenotype and inhibit the accumulation of CD8+ T cells in the tumor." (PMID 36358736, 2022). "Using the ART-TIME approach, we identify a AhR-ARNT-mediated co-signaling mechanism between PD-1 and CD2 as a driver in immune evasion of pancreatic ductal adenocarcinoma." (PMID 41372132, 2025). "Along similar lines, TAMs from pancreatic ductal adenocarcinoma (PDAC) display high AHR activity and AHR deletion in macrophages promotes an inflammatory state." (PMID 37740232, 2023).
stomach tumors (16 papers, 2009 to 2025). "AHR-deficient cancer models have demonstrated increased tumorigenesis while constitutive activation of AHR induces gastric tumor formation." (PMID 34149693, 2021). "Increased AhR staining score in the primary gastric tumor highly associated with the presence of distant metastasis." (PMID 25226618, 2014). "Aryl hydrocarbon receptor (AhR) functions as a ligand-activated basic helix-loop-helix transcription factor regulating transcription encoding xenobiotic metabolizing enzymes, which has been shown constitutively active AhR induces stomach tumors." (PMID 25226618, 2014). "In the study presented here, we have analyzed the expression of AhR and several AhR-regulated genes in a series of gastric tumors including diffuse and intestinal GC." (PMID 39200369, 2024). "As compared to the normal gastric tissue samples, AhR expression was significantly increased in gastric tumors (×1.94, p = 0.002), both diffuse and intestinal GC (×2.12, p = 0.001 and ×1.60, p = 0.003, respectively)." (PMID 39200369, 2024). "In transgenic mice, a constitutively active AhR induces stomach tumors demonstrating an oncogenic potential of the AhR." (PMID 31417567, 2019). "Taken together, these findings suggest that the therapeutic activation of Calpain-10 by Biseugenol-treated and further interaction with AhR suppresses both gastric tumor growth and peritoneal dissemination by inducing ER." (PMID 25226618, 2014). "Taken together, these data suggest that Calpain-10 activation and AhR inhibition by Biseugenol impedes both gastric tumor growth and peritoneal dissemination by inducing ER stress and inhibiting EMT." (PMID 25226618, 2014). "The tumorigenic function of the AhR is underscored by the fact that constitutively active AhR induces stomach tumors in rodents." (PMID 20565777, 2010). "AHR overexpressing mice are prone to stomach tumors and intestinal metaplasia precancerous lesions." (PMID 27129165, 2016). "Interestingly, IDO1 levels, but not IDO2 levels (not expressed), were significantly elevated in high AhR expressing gastric tumors." (PMID 35203450, 2022).
thyroid cancer (16 papers, 2015 to 2023). "This AHR/CYP2S1 feedback loop strongly amplifies oncogenic role of BRAFV600E in thyroid cancer cells, thereby causing synthetic lethal interaction between CYP2S1 and BRAFV600E." (PMID 32913191, 2020). "To investigate if AhR overexpression in thyroid cancers was associated with the activation of its transcriptional activity, we evaluated the expression levels of AhR target gene CYP1B1." (PMID 31936153, 2020). "This AHR/CYP2S1 feedback loop strongly amplified oncogenic role of BRAFV600E in thyroid cancer cells, thereby causing synthetic lethal interaction between CYP2S1 and BRAFV600E." (PMID 32913191, 2020). "The obtained results suggest that AhR is implicated in thyroid cancer initiation and progression both promoting the establishment of an immunosuppressive tumor microenvironment and EMT." (PMID 31936153, 2020). "Of interest, AhR has been shown to be upregulated in thyroid cancer samples and functionally favor the acquisition of a mesenchymal phenotype in thyroid cancer cells." (PMID 38098751, 2023). "In particular, high expression of AhR was statistically correlated with a more aggressive histotype of thyroid cancer: 14 PDTC/ATC (93%) showed a high AhR expression (p < 0.001)." (PMID 34640369, 2021). "Previously published findings have indicated that AhR was up-regulated in thyroid cancer, but the role of AhR in the differentiation of PTC was still unclear." (PMID 35002727, 2021). "This AhR/CYP2S1 feedback loop strongly amplifies oncogenic role of BRAFV600E in thyroid cancer cells." (PMID 35002727, 2021). "AhR expression was assessed by qPCR in 107 thyroid cancer samples (90 PTCs, 11 MTCs, 6 ATCs), and by immunohistochemistry in 41 PTCs." (PMID 31936153, 2020). "To more deeply investigate the role of IDO1-kynurenine-AhR in thyroid cancer, we analyzed AhR expression in a collection of tissues (90 PTCs, 11 MTCs and 6 ATCs) as mRNA or, in a subgroup of 41 PTCs, as protein." (PMID 31936153, 2020). "After having evaluated expression and activation state of AhR in human thyroid cancer samples, we analyzed AhR and CYP1B1 expression in human thyroid carcinoma cell lines." (PMID 31936153, 2020). "Our finding is comparable with the observation published previously showing that kyn induced AhR activation enhanced invasiveness in thyroid cancer cells." (PMID 33542896, 2020). "We evaluated AhR expression in thyroid cancer samples derived from transgenic mice characterized by conditional expression of BRAFV600E in the thyroid." (PMID 31936153, 2020). "AhR was measured by IHC in 14 thyroid cancers, 4 normal thyroids and 2 lymph node metastases derived from 3 different mouse models kindly provided by Dr. Jeffrey Knauf (Memorial Sloan Kettering Cancer Center, New York)." (PMID 31936153, 2020). "To deeper investigate the role of the IDO1-Kynurenine-AhR pathway in thyroid cancer pathogenesis, we analyzed AhR expression in human-derived thyroid cancers and in thyroid tumors from BRAF-transgenic mice." (PMID 31936153, 2020). "AhR mRNA expression resulted significantly higher in all the analyzed thyroid cancer samples compared to normal thyroid and a statistically significant correlation with CYP1B1 was detected." (PMID 31936153, 2020). "Evaluation of AhR mRNA expression in human thyroid carcinoma cell lines showed overexpression of the receptor in four to six." (PMID 31936153, 2020). "To evaluate the functional effects of AhR activation in thyroid carcinomas, we selected the FTC-133 and BcPap cell lines for further studies." (PMID 31936153, 2020). "More recently, investigating the role of genetic events responsible for the onset of the thyroid cancer in acromegaly, we have shown that AHR is selectively overexpressed in a small cohort of PTC compared to the normal surrounding tissue." (PMID 26392334, 2015).
thyroid cancer (continued). "Additionally, the IDO1-Kyn-AhR pathway is a critical regulator of the immunosuppressive microenvironment and favors the acquisition of a mesenchymal phenotype in thyroid cancer." (PMID 36831659, 2023). "The high expression of AhR in thyroid cancer, as well as its oncogenic function in thyroid cancer, prompted us to investigate whether inhibiting AhR nuclear translocation by AhR antagonists induces differentiation of PTC." (PMID 35002727, 2021). "Previous research found that AhR was overexpressed in thyroid cancer, particularly in BRAFV600E mutant ones, and it participated in thyroid cancer initiation and progression by regulating the establishment of an immunosuppressive tumor microenvironment and the epithelial to mesenchymal transition." (PMID 35002727, 2021). "In thyroid-tumor samples, the AhR target genes CYP1A1 and CYP1B1 were upregulated relative to associated healthy tissue and again Kyn stimulation of thyroid-cancer cell lines promoted the acquisition of an EMT program (decreased E-cadherin, and increased SLUG, N-cadherin, and fibronectin levels)." (PMID 33451095, 2021). "It has been confirmed that the IDO1–Kyn–ligand-activated transcription factor (AhR) pathway in thyroid cancer cells would facilitate epithelial-to-mesenchymal transition (EMT), while Kyn depletion in vivo would reverse IDO1-mediated cancer immune suppression in an animal model." (PMID 35003126, 2021). "Overall, these data suggested an involvement of kynurenine-induced AhR activation in conferring a more aggressive phenotype to thyroid cancer cells, by contributing to the onset of an immune-tolerant microenvironment and promoting cellular migration and invasiveness." (PMID 31936153, 2020). "Furthermore, we evaluated the AhR-mediated transcriptional and functional effects of kynurenine in two human thyroid cancer cell lines." (PMID 31936153, 2020). "This study evaluated AhR expression and its role in thyroid cancer progression." (PMID 31936153, 2020). "AHR has been reported to be overexpressed and constitutively active in a variety of solid tumors, but few data are currently available concerning its role in thyroid cancer." (PMID 26392334, 2015). "This study confirmed the importance of the IDO1-Kyn-AhR pathway in thyroid cancer tumorigenesis, suggesting an AhR pivotal role in mediating an immunosuppressive microenvironment and favoring the acquisition of a mesenchymal phenotype that could promote invasiveness and metastasis." (PMID 31936153, 2020). "Moreover, TF AHR could positively regulate target gene DLL4 to cause the migration and angiogenesis of thyroid cancer cells." (PMID 31126066, 2019). "Indeed, based on the study findings, we could advance the potential role of AhR/N-cadherin as a prognostic marker, being able to suggest a more aggressive phenotype in thyroid carcinoma as evidenced by the high levels of AhR/N-cadherin found in most patients of the PTC-A and PDTC/ATC groups." (PMID 34640369, 2021). "Based on the current knowledge regarding potential biomarkers of tumour aggressiveness, Aryl hydrocarbon receptor (AhR), N-cadherin, E-cadherin and CD147 were selected to be analysed in thyroid carcinomas for the following reasons." (PMID 34640369, 2021). "In a poorly differentiated thyroid carcinoma (PDTC) cell line, kynurenine-driven activation of AhR induced epithelial–mesenchymal transition (EMT) involving cadherins." (PMID 34640369, 2021). "The level of AhR functional activation was evaluated by measuring CYP1A1 and CYP1B1 mRNA expression in the thyroid cancer samples." (PMID 31936153, 2020).
acute kidney injury (15 papers, 2017 to 2025). Sudden and sustained deterioration of the kidney function characterized by decreased glomerular filtration rate, increased serum creatinine or oliguria. "Uremic toxin indoxyl sulfate (IS) causes vascular inflammation via the aryl hydrocarbon receptor (AhR), resulting in renal failure." (PMID 39113916, 2024). "Acute kidney injury (AKI) is a significant complication of malaria that is linked to heme metabolism and the generation of AhR agonists." (PMID 38680494, 2024). "The Nrf2-dependent induction of miRNAs was shown to interact with other molecular pathways, as miR-125b is increased by Nrf2, and inhibited aryl hydrocarbon receptor (AhR) repressor, which contributed to the protection from acute kidney injury." (PMID 28862664, 2017). "In addition, oral administration of chrysin attenuated the deterioration of renal failure induced by IS in mice, probably via its suppressive effect on IS-mediated AhR activation." (PMID 39113916, 2024). "AhR activation enhances nuclear translocation and expression of nuclear factor erythroid 2-related factor 2 (NRF2), reduces reactive oxygen species (ROS) accumulation, and inhibits ferroptosis, providing a potential therapeutic target for the treatment of acute kidney injury (AKI)." (PMID 41150072, 2025).
celiac disease (15 papers, 2019 to 2026). An autoimmune genetic disorder with an unknown pattern of inheritance that primarily affects the digestive tract. "Patients with celiac disease have reduced levels of endogenous AhR ligands and consequently less intestinal AhR activity, and AhR knockout mice were found to be more susceptible to dextran sulfate sodium -induced colitis." (PMID 38448800, 2024). "The third trial, Tryptophan for Impaired AhR Signaling in Celiac Disease (TIARSCeD), is currently ongoing." (PMID 40942152, 2025). "Gut-microbiota-dependent AhR ligand production and intestinal AhR pathway activation are decreased in celiac disease, leading to intestinal inflammation." (PMID 39767818, 2024). "AhR mRNA and protein expression is diminished in the intestinal mucosa of patients with active Celiac disease." (PMID 39767818, 2024). "In the intestinal mucosa of active celiac disease patients, AhR expression is downregulated." (PMID 38396767, 2024). "Another way these bacteria might influence celiac disease development is through the production of aryl hydrocarbon receptor (AhR) ligands." (PMID 38396767, 2024). "This indicates clearly that the AHR deficiency documented in CD, as well as in celiac disease mucosa by itself, should not be sufficient to drive pathology." (PMID 38674118, 2024). "Individuals with IBD and celiac disease have low levels of AhR in their feces." (PMID 36296244, 2022). "In this study, we investigated the role of AhR in celiac disease (CD), a gluten-driven enteropathy." (PMID 30778350, 2019). "It is noteworthy that the AhR pathway controlled the phenotypic changes in ILCs populations found in the inflamed terminal ileum of individuals with celiac disease, as indicated by the ILC3 to ILC1 shift and a downregulation of AhR expression in the intestinal ILCs." (PMID 39211042, 2024). "L. reuteri can transform tryptophan into AhR agonists, but combination of L. reuteri and tryptophan did not further reduce disease severity in celiac disease mice, suggesting that a low abundance of L. reuteri is enough to produce sufficient AhR agonists and mediate disease outcomes." (PMID 34297785, 2021).